MTOR (mechanistic target of rapamycin kinase)
Diseases named in the same sentence as MTOR in open-access papers (continued):
Sharing a sentence is not in itself a finding about the gene and the disease.
infection (continued). "Independent of infection, DptA, along with other AMPs, is induced by FOXO in response to nutrient stress, or in response to mTOR inhibition by rapamycin, and their induction is required for timely larval development." (PMID 39135281, 2024). "Pharmacological approaches employed in the present study also revealed that infection-induced phosphorylation of AKT and FOXO3a in HFF do not require mTOR activity." (PMID 37387601, 2023). "In contrast, under pathological conditions (infection or drug treatment), elevated phosphorylated ULK1 (ser 757) protein initiates autophagy, and high mTOR activity does not completely prevent ULK1 (ser 757) phosphorylation to inhibit autophagy in cells." (PMID 36148236, 2022). "We found that inhibitors of AKT, mTOR, and PI3K completely abolished the expression of NF-E2 and GATA2 with or without infection, suggesting that these proteins had a significant role as regulatory molecules of megakaryopoiesis process." (PMID 34513730, 2021). "The results showed that mTOR was activated in MCF-7/ADR cells, but not in MCF-7 cells, and that the activity of mTOR in MCF-7/ADR cells was inhibited infection with Ad-VT." (PMID 34869595, 2021). "An inhibited levels of mTOR and PDI-2 in western blot analysis suggested that the regulatory proteins are not folded properly in C. elegans during infection." (PMID 28932706, 2017). "To confirm the negative role of mTOR in PDCoV infection, we monitored dynamic mTORC1 activity by assessing the expressions of P70S6K, p-P70S6K, 4EBP1, p-4EBP1 at specific time points post infection." (PMID 39891192, 2025). "Furthermore, a significant upregulation of MTOR expression was noted upon Mtb HN878 and not CDC1551 infection of the macrophages trained and restimulated with LPS or PPD." (PMID 38980014, 2024). "Intriguingly, during lytic infection miR-UL36, miR-UL112, and miR-UL148D only affect activation of a subset of the tested Akt effectors, including FOXO3a, PRAS40, and Akt itself, but not other effectors like CREB, mTOR, and P70S6K." (PMID 39661658, 2024). "We also showed a significantly reduced level of protein biosynthesis (mTOR signaling), lipid biosynthesis (SREBP signaling) and glucose uptake (AMPK activation) and glycolysis (HK2) in the lungs during infection in adult mice irrespective of diet." (PMID 35329973, 2022). "Upon host cell infection, a pore forming toxin, Listeriolysin O (LLO) triggers a rapid inhibition of host amino acids synthesis, characterized by the inhibition of mTOR leading to induction of noncanonical autophagy involving recruitment of LC3 on the damaged Listeria-containing vacuole." (PMID 33735319, 2021). "Then, we analyzed the phosphorylation status of 4E-BP1 and S6, as substrates of mTOR activity, and we observed a significant increase of 4E-BP1 and S6 phosphorylation after 2 hpi, which was not evident after 6 h of infection, both facts supporting an early activation of mTOR." (PMID 33384682, 2020). "This might indicate that the absence of co-stimulation during the acute phase of infection due to increased expression of inhibitory molecules, such as CTLA-4, which may allow GRAIL expression to be maintained via a blockade of mTOR activation." (PMID 28114324, 2017). "Importantly, mTOR suppresses factor inhibiting HIF-1 (FIH-1), a negative regulator of HIF-1α57, and FIH-1 may represent one central node congregating mTOR and HIF-1α signaling towards the activation of glycolysis in response to infection." (PMID 32385235, 2020).
neurodegenerative disease (219 papers, 2010 to 2025). A disorder of the central nervous system characterized by gradual and progressive loss of neural tissue and neurologic function. "Inhibition of mTOR restored lysosomal acidification and rescued this phenotype associated with neurodegenerative diseases." (PMID 40065324, 2025). "The dysregulation of pathways such as EIF2 signaling and mTOR signaling has been implicated in various pathological conditions, including tumorigenesis, neurodegenerative diseases, and metabolic disorders." (PMID 40872491, 2025). "The PI3K/Akt/mTOR signalling pathway has been associated with neurodegenerative diseases and is involved in regulating a wide range of upstream molecules, including those related to inflammation and oxidative stress." (PMID 39457495, 2024). "mTOR plays a role in autophagy-related processes, and dysfunction within mTOR pathways has been associated with neurodegenerative diseases." (PMID 38920976, 2024). "Recently, more and more studies are focused on the potential therapeutic effects of mTOR inhibitors in neurodegenerative diseases that are linked with oxidative stress." (PMID 35883796, 2022). "The close involvement of the Nrf2/ARE signaling pathway in mTOR function and its association with neurogenesis and neurodegenerative diseases can open new prospective treatments for numerous neurodegenerative diseases." (PMID 35805130, 2022). "mTOR regulates the transcription and translation of hypoxia inducible factor 1α (HIF1α), which mediates mechanisms associated with stroke and neurodegenerative diseases." (PMID 36353499, 2022). "The mammalian target of rapamycin (mTOR) is a key molecule in the mTOR signaling pathway and has been associated with many diseases, such as metabolic disorders and degenerative diseases." (PMID 36035226, 2022). "Dysfunction of the mammalian target of rapamycin (mTOR) pathway has been implicated in both neurodevelopmental and neurodegenerative diseases, including AD." (PMID 33490374, 2021). "A growing number studies have already noted that AKT/mTOR pathway is implicated in the process of neurodegenerative disease, such as, mTOR pathway plays a critical role in the regeneration and synaptic plasticity after central nervous system injury." (PMID 32424108, 2020). "Nevertheless, as stated in a recent review paper, succinate is linked with the mammalian target of rapamycin (mTOR), a kinase involved with a plethora of neurodegenerative diseases." (PMID 33153035, 2020). "Next, we used rapamycin, an inhibitor of mammalian target of rapamycin (mTOR) implicated in various neurodegenerative diseases." (PMID 29145487, 2017). "Alterations in the Akt-mTOR and Wnt-β-catenin pathways are both linked to the pathology of neurodegenerative diseases." (PMID 28515679, 2017). "We also need to understand which mechanisms spatiotemporally modulate or balance mTOR expression and how their disruption is associated with neurodegenerative diseases." (PMID 27378854, 2016). "The autophagy system is further implicated in neurodegenerative diseases of ageing, since inhibition of the mammalian target of rapamycin (mTOR), which is well known to induce autophagy, was found to prolong the lifespan in lower organisms and mammals." (PMID 24307901, 2013). "Furthermore, mTOR activation prevents neuronal loss, blocks oxidative stress-induced microglial damage, and protects against neuronal damage and neurodegenerative diseases." (PMID 41009813, 2025). "Furthermore, the dysregulation of the PI3K/AKT/mTOR pathway in MMVD supports the concept that this degenerative disease is associated with tissue ageing." (PMID 36869852, 2023). "mTOR plays an important role in the body and its mutation or dysregulation has been associated with diseases such as cancer, cardiovascular disease, obesity, inflammation, diabetes, and neurodegenerative disease." (PMID 35805130, 2022).
neurodegenerative disease (continued). "However, dysregulation in neurogenesis, mTOR, and Nrf2 activity have all been associated with neurodegenerative diseases such as Alzheimer’s, Huntington’s, and Parkinson’s." (PMID 35805130, 2022). "The mTOR pathway has been extensively implicated in neurodegenerative diseases, mainly because the overactivation of mTORC1 effectively inhibits autophagy, and it has been proven that the failure of autophagy degradation is a major culprit in neurodegenerative diseases." (PMID 36466613, 2022). "Indeed, rapamycin (sirolimus; as an mTOR inhibitor) is able to decrease the risk of development of age-related diseases, such as neurodegenerative diseases, to improve age-related decrease in memory and learning functions and to extend longevity." (PMID 34206738, 2021). "Furthermore, dysregulation of autophagic pathways, such as the mammalian target of rapamycin (mTOR) signaling pathway, has been implicated in many neurodegenerative diseases." (PMID 31500666, 2019). "Although few studies have evaluated the role of mTOR in traumatic brain injury and genetic models of neurodegeneration, its role in the pathological processes associated with excitotoxic injury, an event present in neurodegenerative diseases, is poorly understood." (PMID 28143498, 2017). "The mammalian target of rapamycin (mTOR), a master negative regulator of autophagy, plays a pivotal role in the pathogenesis of neurodegenerative diseases, including ALS." (PMID 40135564, 2025). "The role of mTOR signaling in degenerative diseases such as ALS and other related conditions lies in its ability to inhibit autophagy, which prevents the elimination of misfolded proteins (cellular waste), contributing negatively to the disease." (PMID 40299664, 2025). "Overall, these preclinical results suggest that PF-04691502 holds promise as a potential therapeutic agent for AD and other aging-related neurodegenerative diseases involving mTOR pathway dysregulation." (PMID 41002439, 2025). "AMPK and mTOR participate in the development of neurodegenerative diseases during aging through autophagy." (PMID 40119168, 2025). "In neurodegenerative diseases, altered flux through mTOR signaling affects mitochondrial fission and fusion, contributing to disease pathogenesis." (PMID 40450326, 2025). "We now demonstrate that exogenous expression of miR-217 significantly reduced STAU2 and mTOR levels in cellular models of neurodegenerative disease." (PMID 39955058, 2025). "KEGG pathway analysis revealed that the most enriched pathways included the PI3K-AKT signaling pathway, AD pathology, ROS-related carcinogenesis, neurodegenerative disease pathways, apoptosis, neurotrophin signaling, mTOR signaling, and autophagy." (PMID 40817000, 2025). "The mTOR signaling axis has been shown to be severely deregulated in various neurodegenerative diseases, particularly AD." (PMID 38659706, 2024). "It includes the WNT and PI3K/AKT/mTOR pathways, which, when dysregulated, lead to neurodegenerative diseases." (PMID 39051304, 2024). "Although herbal/natural compounds overlap with most conventional therapies for neurodegenerative diseases in terms of the molecular pathways targeted, such as the mTOR signaling pathway, traditional medicines have the advantage of low toxicity." (PMID 37107295, 2023). "In neurodegenerative diseases, AMPK/mTOR pathway stimulation is associated with curbing the cognitive deficit and AD neuropathology by the removal of amyloid aggregates and p-tau." (PMID 37765022, 2023). "Some important pathways are WNT and PI3K/AKT/mTOR, and their dysregulation results in digestive neoplasia and neurodegenerative diseases." (PMID 37509697, 2023). "Mammalian target of rapamycin (mTOR) is an evolutionarily conserved serine/threonine kinase that plays a vital role in diverse degenerative diseases." (PMID 36193577, 2023). "Melatonin prevents degenerative diseases in the nervous system by inhibiting apoptosis through regulation of the mTOR-mediated pathway." (PMID 37937274, 2023).
neurodegenerative disease (continued). "We found that Ngfr expression reduced pathways related to neurodegenerative diseases, including AD, while induced pathways related to sustained homeostasis and growth, such as proteasome, mTOR signaling and cell cycle." (PMID 37429840, 2023). "There is sufficient evidence to suggest implications of dysregulated mTOR signalling in MAP-Tau pathology observed in these neurodegenerative diseases." (PMID 37108467, 2023). "In the same vein, we note the fact that miR-129-5p targets similar pathways (PI3K/AKT/mTOR pathways) in both digestive diseases and in neurodegenerative diseases." (PMID 37509697, 2023). "Some important pathways include the WNT and PI3K/AKT/mTOR pathways; their dysregulation results in digestive neoplasia and neurodegenerative diseases." (PMID 37509697, 2023). "Many of the therapies targeting the lysosomal pathway in neurodegenerative diseases rely on the mTOR signaling pathway, and most of these drugs have antidepressive actions." (PMID 37107295, 2023). "In conclusion, the SLC38A10 knockout model revealed the new finding of SLC38A10 in glutamate metabolism, mTOR dependent protein and fatty acid regulation, supporting a previous association between SLC38A10 polymorphisms and neurodegenerative diseases." (PMID 35450293, 2022). "The sterol-response binding proteins (SREBPs) are one of the transcription factors regulated by mTOR and are involved in nutrient sensing, excitotoxicity, myelination and neurodegenerative diseases." (PMID 36353499, 2022). "Here, we review both mTOR and Nrf2 complexes, their crosstalk and role in neurogenesis, and their implication in neurodegenerative diseases." (PMID 35805130, 2022). "Since AMPK regulates mTOR activity, and both have been shown to be deregulated in neurodegenerative diseases, we also checked for mTOR activation." (PMID 36127342, 2022). "Contributes to lysosomal function as well as the viability of neurones; mutations in CLN6 have shown to cause neurodegenerative disease; CLN6 is also associated with mTOR and TELO2 regulators of signaling pathways that are known to be disrupted by ZIKV." (PMID 35371036, 2022). "The finding reported in this review highlights that in neurodegenerative diseases like retinopathy, the mTOR pathway can be over activated or inhibited." (PMID 36388931, 2022). "Epigallocatechin-3-gallate promotes dendritic growth and synaptogenesis through selective inhibition of the AKT/mTOR signaling pathway, inhibits acetylcholinesterase activity, and effectively ameliorates neurological damage in neurodegenerative diseases." (PMID 36225188, 2022). "Rapamycin, an inhibitor of the mammalian target of rapamycin (mTOR) pathway, and its derivatives are among the most studied therapeutic agents for the treatment of neurodegenerative diseases, including PD and HD." (PMID 36340034, 2022). "The Akt-mTOR signaling pathway is also involved in the progression of various human degenerative diseases, including the degeneration of nucleus pulposus cells." (PMID 35855812, 2022). "We reasoned that in KO PCCs, vacuolar H+ ATPase-dependent lysosomal dysregulation results in an acidification defect in certain neurodegenerative diseases, which would affect the proper movement of the mTOR complex." (PMID 35450293, 2022). "Directly downstream of Akt, mTOR is activated by morphine, yet is repressed by vitamin C; mTOR is central to growth signaling, pathway integration, and numerous degenerative diseases." (PMID 35883757, 2022). "For the downregulated pathways, we observed the regulation of Mitogen-Activated Protein Kinases (MAPK) pathway, PI3K/AKT/mTOR, cytokine and interferon signaling, neurodegenerative diseases, and cell cycle progression and transition-related pathways." (PMID 33627134, 2021).
neurodegenerative disease (continued). "The IPA network showed that these 81 differential metabolites were associated with neuregulin signaling, PI3K-AKT signaling, mTOR signaling, and ERK/MAPK signaling, and all four pathways were associated with neurodegenerative diseases." (PMID 34567412, 2021). "mTOR plays a key role in brain development, neuronal survival, synaptic plasticity, and memory formation and is related to the pathogenesis of neurodegenerative diseases, especially PD." (PMID 34580608, 2021). "The mTOR pathway is also crucial for regulating autophagy, a process that is impaired in aging and defective in neurodegenerative diseases." (PMID 33443781, 2021). "mTOR is a predominant factor of the autophagic process and it is considered as a target to treat neurodegenerative diseases." (PMID 33522352, 2021). "TNFα, oxidative stress, and mTOR (mammalian target of rapamycin) activation are known to induce necroptosis, and the expression or activation of these factors increases with age and neurodegenerative diseases." (PMID 34515928, 2021). "Inhibition of mTOR signaling by rapamycin has been used as a strategy to induce autophagy in order to promote cellular clearance in various aggregation-prone degenerative diseases." (PMID 34685484, 2021). "Abnormal activation of the AKT/mTOR/AMPK signaling pathway inhibits autophagy, and defects affecting this pathway are associated with human neurodegenerative disease." (PMID 34631714, 2021). "It has been reported that the PI3K/mTOR/GSK3β signaling pathway participates in the regulation of various neurodegenerative diseases." (PMID 32832542, 2020). "Along with these illnesses, there is substantial evidence of autophagy dysregulation in neurodegenerative diseases, such as alterations in mTOR and beclin 1 expression, and accumulation of defective autophagosomes." (PMID 32679743, 2020). "Increasing evidence indicates that the mTOR signal is involved in a variety of neurodegenerative diseases ranging from those affecting the central nervous system to eyes." (PMID 32066462, 2020). "Increasing evidence has confirmed that the AKT/mTOR pathway plays a vital role in neurodegenerative diseases, especially in synaptic development and function." (PMID 32514180, 2020). "While references to the most pressing open questions are scattered throughout the abundant literature on mTOR and neurodegenerative disease, herein, we have consolidated these gaps in the literature." (PMID 32903821, 2020). "It is therefore believed that mTOR inhibition should be targeted to protect neurons against age-related neurodegenerative diseases." (PMID 31105084, 2019). "More importantly, many studies have confirmed that rapamycin, a typical MTOR inhibitor, delays the progression of some neurodegenerative diseases." (PMID 30706760, 2019). "The mTor pathway is crucial for regulating mitochondrial biogenesis and autophagy, two processes that are defective in many neurodegenerative diseases." (PMID 30072954, 2018). "Inhibition of the mammalian target of rapamycin (mTOR) pathway has proven to be an exceptionally effective approach for stimulating the degradation of neurodegenerative disease proteins." (PMID 28293421, 2017). "Several mTOR-dependent activators of autophagy, including the natural compounds curcurmin and resveratrol, are currently in clinical trials for treating neurodegenerative diseases." (PMID 28293421, 2017). "Dysregulation of mTOR signaling is emerging as a key component of neurodegenerative disease pathogenesis." (PMID 26971100, 2016). "mTOR inhibition is beneficial in neurodegenerative disease models and its effects are often attributable to the modulation of autophagy and anti-apoptosis." (PMID 27008180, 2016). "Recently, the use of mammalian target of rapamycin (mTOR) inhibitors, in particular rapamycin (Rp), has been suggested to improve the treatment of neurodegenerative diseases." (PMID 28335215, 2016).